POU5F1 (POU class 5 homeobox 1)
Diseases named in the same sentence as POU5F1 in open-access papers (continued):
Sharing a sentence is not in itself a finding about the gene and the disease.
bladder cancer (54 papers, 2008 to 2025). "Additionally, other investigations have revealed that ATRA can impede the expression of POU5F1 in bladder cancer cells, thereby rendering these cells less susceptible to destruction induced by oncolytic adenovirus carrying POU5F1 response element (ORE)." (PMID 38062041, 2023). "Hence, POU5F1 could be useful as a diagnostic biomarker as well as a prognosis biomarker for the prediction of recurrence risk and the survival of bladder cancer patients." (PMID 37627900, 2023). "Taken together, the presence of POU5F1 expression in bladder cancer tissues and cell lines suggests that POU5F1 promotes bladder tumorigenesis." (PMID 37627900, 2023). "Previous studies have shown that POU5F1 is highly expressed in bladder cancer, which is consistent with our findings." (PMID 36685927, 2022). "POU5F1 can enhance tumour immune response by upregulating the TET1-dependent NRF2/MDM2 axis in bladder cancer." (PMID 36685927, 2022). "Then, the expression of previously identified bladder cancer stem cell markers (POU5F1, BMI1, NANOG, SOX2,) was determined by real- time qPCR in the established control NT and αv kd cell lines as well as in GLPG0187 treated cells." (PMID 25247809, 2014). "The high expression levels of MMPs have been observed in the bladder cancer cells overexpressing POU5F1, suggesting that overexpression of POU5F1 upregulates genes of MMPs." (PMID 24386189, 2013). "POU5F1 has also been shown to have an important role in bladder cancer stem cells, invasion and migration, however, our data suggest that αv integrin might affect migration through a mechanism independent of POU5F1, for example via NANOG or SOX2." (PMID 25247809, 2014). "IRF5 (p=0.055), CCN1 (p=4.1e-08), MYC (p=0.039), POU5F1 (p=0.027), and TGFB1I1 (p=6.5e-08) were significantly differentially expressed at different stages of bladder cancer." (PMID 37433010, 2023). "The majority of the FFPE bladder cancer tissues showed positive OCT4 (also known as POU5F1) expression with a variety of intensities, thus indicating that OCT4 is heterogeneously expressed in bladder cancer cells." (PMID 37627900, 2023). "Published literatures have certified that increased POU5F1 was correlated with clinicopathological features and prognosis not only in LIHC, but also in bladder carcinoma, non‐small cell lung carcinoma, and oral squamous cell cancer." (PMID 32978904, 2020). "Similarly, in TCGA database bladder cancer samples, CCN1 (p=7.9e-07), MYC (p=0.0043), POU5F1 (p=0.021), and TGFB1I1 (p=6.0e-05) had significant differences in bladder cancer high-grade and low-grade samples, in addition to IRF5 (p=0.2)." (PMID 37433010, 2023).
colon carcinoma (51 papers, 2011 to 2025). "It shares a high similarity (95%) with isoform 1 of POU5F1 and is positioned near a genetic variant (rs6983267) strongly linked to increased prostate and colon cancer risk." (PMID 40556338, 2025). "For instance, obesity‐induced inflammation led to hypomethylation of the promoter regions of oncogenes such as Nanog homeobox, POU class 5 homeobox 1 (POU5F1), and MYC proto‐oncogene (MYC) in colon cells, which may eventually cause colon cancer." (PMID 38405061, 2024). "The POU5F1 transcription factor is essential for the maintenance of self-renewal, and its high expression in residual cancer cells after radiochemotherapy is correlated with poor prognosis in colon cancer." (PMID 22970250, 2012). "In colon cancer, DOT1L increases cancer stemness and tumorigenic potential by inducing the core stem cell genes NANOG, SOX2 and Pou5F1." (PMID 27581651, 2016).
seminoma (45 papers, 2008 to 2026). A radiosensitive malignant germ cell tumor found in the testis (especially undescended), and extragonadal sites (anterior mediastinum and pineal gland). "Key transcription factors (TFs) such as TFAP2C, SOX17, OCT4/POU5F1 and NANOG are highly expressed in PGCs, and consequently are excellent diagnostic markers for seminoma and GCNIS14,18,19." (PMID 38123589, 2023). "The POU5F1 locus is covered by 18 CpG sites on the array platform that collectively displayed a hypomethylated state in seminomas as compared to d0-PTCs and LT-PTCs, including the genomic region directly upstream of the transcription start site." (PMID 32176716, 2020). "Gankyrin was also detected in the cytoplasm of seminoma tumour cells and the seminoma component of mixed non-seminoma, which was determined by POU5F1 expression." (PMID 31744479, 2019). "Metastatic tumor cells expressed another marker gene for seminoma, POU5F1." (PMID 35494058, 2022). "In contrast to seminomas, the POU5F1 transcript was virtually undetectable by qPCR in PTCs after culture, which would argue against the presence of even a small number of tumorigenic cells, although these data are not enough to rule out the presence of trace amounts of malignant cells completely." (PMID 32176716, 2020). "To confirm the activated gene expression of POU5F1 in seminomas we performed gene expression analysis of the POU5F1 isoform 1 transcript (NM_002701) by qPCR and found high expression levels in seminomas while it was nearly undetectable in PTCs both before and after culturing." (PMID 32176716, 2020). "Utilizing the SCENIC analysis on the non-seminoma tumor cells, we observed heightened activity of transcription factors quintessential for pluripotency maintenance, notably NANOG, POU5F1, and HDAC2, within the EC subset." (PMID 39528470, 2024). "We found that seminoma and PGCs display strong similarities in their transcriptomes, especially by sharing the expression of key TFs such as TFAP2C, POU5F1, NANOG and SOX17." (PMID 38123589, 2023). "Notably, TFAP2C and POU5F1 were highly enriched in seminoma, re-enforcing our findings based on scRNA-seq that these key TFs may play an important role in seminoma." (PMID 38123589, 2023). "As expected, seminoma and PGCs shared specific expression of genes (C2) such as TFAP2C, POU5F1, NANOG and SOX17." (PMID 38123589, 2023). "TSPO protein expression was assessed in paraffin sections from several seminoma cases, in parallel with pluripotency genes OCT3/4 (OCT4; POU5F1) and AP2γ (TFAP2C), considered as seminoma markers." (PMID 27608010, 2016). "The core stemness transcription factors POU5F1 and NANOG which are expressed in both, seminoma and non-seminoma tumor cells are thought to be pivotal for the identification of TGCT." (PMID 23969837, 2013). "POU5F1, also named OCT4, has been identified as a marker gene for seminoma previously." (PMID 35494058, 2022). "The pivotal POU5F1 marker was hypomethylated in seminomas but not in uncultured or cultured primary testicular ITGA6+ cells, which is reflected in the POU5F1 mRNA expression levels." (PMID 32176716, 2020). "In addition, seminomas can display genetic mutations in the KIT gene and they express the pluripotency marker POU5F1, which is not detectable in normal testis." (PMID 32176716, 2020). "Other genes displayed differences, because OCT4/POU5F1, a pluripotency marker, was hypomethylated in seminomas but not in uncultured or cultured primary testicular cells, while DPPA3 and XIST were hypermethylated only in long-term cultured cells." (PMID 38791003, 2024).
osteosarcoma (40 papers, 2010 to 2025). A usually aggressive malignant bone-forming mesenchymal neoplasm, predominantly affecting adolescents and young adults. "Previous studies have reported that Pou5f1 works in maintaining the cancer stem cell fate of osteosarcoma." (PMID 33829012, 2021). "Previous studies have reported that POU5F1 plays an extremely important role in maintaining the cancer stem cell fate of osteosarcoma." (PMID 28239298, 2017). "Taken together, our results for the first time showed the relationship between miR-335 and POU5F1 in osteosarcoma stem cells." (PMID 28239298, 2017). "Out of the differentially modulated genes, those implicated in stem cell and osteosarcoma biology, such as PPARG, ETS1, WNT1, WNT5B, SOX2, NANOG, POU5F1, nestin, and ALDH were chosen for further analysis." (PMID 22870217, 2012). "Thirdly, there are plenty of genes targeted by miR-335, it is unknown whether genes except POU5F1 also participate in regulating osteosarcoma stem cells." (PMID 28239298, 2017). "The current study demonstrates that miR-335 negatively regulates osteosarcoma stem cell-like properties by targeting POU5F1, and miR-335 could target CSCs to synergize with traditional chemotherapeutic agents to overcome osteosarcoma." (PMID 28239298, 2017). "Furthermore, miR-335 inhibited stem cell-like properties via suppression of POU5F1 in osteosarcoma." (PMID 35252166, 2022). "Therefore, identification of TSCs based on POU5F1, SOX2, or NANOG expression remains controversial, at least in osteosarcoma." (PMID 22870217, 2012).
germ cell tumor (31 papers, 2008 to 2025). A benign or malignant, gonadal or extragonadal neoplasm that originates from germ cells. "Prior research has demonstrated the involvement of POU5F1 in the differentiation and regulation of embryonic stem cells, leading to its predominant expression in embryonic and germ cell tumors." (PMID 38062041, 2023). "All types of germ cell tumors and ECCs expressed high levels of 58 genes associated with genomic imprinting and the regulation of pluripotency (NANOG, OCT4/POU5F1, GAL, DPPA4, NALP7, etc.)." (PMID 31771212, 2019). "Recent reports on human POU5F1 pseudogenes suggested - especially in somatic cells, tissue-specific stem cells, and non-germ cell tumours - that some re-evaluation of expression data on POU5F1 might be needed due to the use of primers which cannot distinguish pseudogenes from the coding one." (PMID 19732419, 2009). "Gonadal biopsy and immunohistochemical biomarkers (OCT3/4 (POU5F1), TSPY, SOX9, FOXL2 and KITLG (SCF)) are important to characterize situations in which GCC development is possible (germ cells tumors)." (PMID 31721911, 2019). "Moreover, we confirmed that LTR5_Hs were preferentially bound by KLF4, NANOG, POU5F1, and TFAP2C in naïve ESCs, by TFAP2C in PGCLCs, and by SOX17 in a germ cell tumor cell line using publicly available ChIP-Seq datasets." (PMID 35551519, 2022). "Few data exist on expression of the different POU5F1 isoforms in germ cells or germ cell tumor tissue, since most expression studies to date have not discriminated between the two isoforms." (PMID 18254969, 2008). "In non-diseased tissue and tissue from non-germ cell tumors, POU5F1 expression is virtually undetectable." (PMID 18254969, 2008). "POU5F1 is highly expressed in nearly all adult seminomas, embryonal cell carcinomas, and testicular carcinoma in situ (CIS), but not childhood TGCC or spermatocytic carcinomas, or non-germ cell testicular cancers." (PMID 18254969, 2008).
lymph node metastasis (24 papers, 2012 to 2024). "On the other hand, lower expression of the CSC-associated genes ALDH1A3, LGALS3 and MYH9 and the pluripotency gene POU5F1 assessed by fingerprint values, were instead associated with the presence of lymph node metastases (LN Met)." (PMID 38124067, 2023). "However, there are currently few studies on POU5F1/Oct-4 as an indicator of lymph node metastasis." (PMID 26931354, 2016). "POU5F1/Oct-4 expression levels in tissues obtained from patients with sentinel lymph node (SLN) and non-SLN metastasis and in tissues obtained from patients without lymph node metastases were compared." (PMID 26931354, 2016).
oral cancer (21 papers, 2009 to 2025). "For example, oral cancer cells overexpressing the core pluripotency factors SOX2 and POU5F1/OCT4 in xenograft mouse model assays were thought to represent reprogrammed cells capable of inducing tumorigenesis." (PMID 37761874, 2023).
head and neck squamous cell carcinoma (19 papers, 2015 to 2024). A squamous cell carcinoma that arises from any of the following anatomic sites: lip and oral cavity, nasal cavity, paranasal sinuses, pharynx, larynx, and salivary glands. "The Rickman Head and Neck Cancer gene set is positively correlated with POU5F1 and SOX2 gene expression and consists of genes identifying an intrinsic group in head and neck squamous cell carcinoma (HNSCC)." (PMID 32899474, 2020).
sarcoma (19 papers, 2011 to 2025). A usually aggressive malignant neoplasm of the soft tissue or bone. "In 7 tested sarcoma cell lines, POU5F1 mRNA expression levels were significantly higher in cells surviving trabectedin compared to untreated controls, olaparib, and combination treatments." (PMID 40986050, 2025). "Furthermore, approximately 50% of myoepitheliomas have translocations involving the EWSR1 gene, such as EWSR1::POU5F1 sarcoma, and myoepithelioma can also exhibit positive expression of CD99 and NKX3.1, posing a significant diagnostic challenge." (PMID 38254207, 2024). "Survival analysis revealed that higher expression of SOX2, NANOG, and MYC but not OCT4 (POU5F1) or KLF4 is associated with significantly reduced survival in sarcoma patients." (PMID 36506091, 2022). "We showed that IRF3 specifically binds to the POU5F1 promoter region and directly stimulates gene transcription in response to cGAS-STING pathway activation in sarcoma cells." (PMID 40986050, 2025).
leukemia (18 papers, 2016 to 2025). A malignant (clonal) hematologic disorder, involving hematopoietic stem cells and characterized by the presence of primitive or atypical myeloid or lymphoid cells in the bone marrow and the blood. "HAP1 cells originate from experiments to induce pluripotency in the leukemia KBM7 cell line by transduction with KLF4, POU5F1 (Oct4), SOX2, and MYC." (PMID 33228647, 2020).
neuroblastoma (17 papers, 2013 to 2025). Neuroblastoma (NB) is the most common solid, extracranial childhood tumor. "Thus, we focused on OCT4 and generated a stable clone of LHN-R with POU5F1 knockdown by transducing five different short hairpin RNA sequences (POU5F1-shRNA-1 to -5) to evaluate the effect of OCT4 on 13-cisRA resistance in neuroblastoma cells." (PMID 32409685, 2020). "Focusing on POU5F1 regulation, it has been shown that PARP1 directly binds to the epigenetic factor PHF20 at the promoter region of POU5F1, activating its transcription in neuroblastoma cells." (PMID 40986050, 2025). "Because POU5F1+ germ cells both in ovaries and adrenals seem to express TUBB3 as well, it may be important to investigate the expression of additional markers to exclude a potential link between neuroblastoma and ‘adrenal’ germ cells." (PMID 26834021, 2016). "SK-N-BE neuroblastoma cells were shown to form CD133+ tumorspheres, unlike SH-SY5Y cells, hence we have first sorted CD133− and CD133+ SK-N-BE cells and showed that expression of CD133, ELK-1, SOX2, NANOG, and POU5F1 were all significantly more in CD133+ cells than in CD133− cells." (PMID 33672811, 2021).
squamous cell carcinoma (16 papers, 2008 to 2025). A carcinoma arising from squamous epithelial cells. "There was a significant decrease in plasma IgG levels for CD25‐MUC1‐VEGFR1 combinations in patients with either adenocarcinoma or squamous cell carcinoma while a significant decrease in plasma IgG levels for POU5F1 in patients with adenocarcinoma." (PMID 32392378, 2020).
medulloblastoma (15 papers, 2010 to 2024). A malignant, invasive embryonal neoplasm arising from the cerebellum. "Expression of LIN28A and POU5F1 has been correlated in medulloblastoma." (PMID 28186969, 2017). "Previous independent studies have shown an intriguing abnormal expression of the pluripotency-related genes POU5F1/OCT4, LIN28B, SOX2 and L1TD1, in medulloblastoma." (PMID 28186969, 2017). "Here, a more detailed analysis revealed that, from all alternative POU5F1 transcripts investigated, only OCT4A transcript levels significantly correlated with LIN28A expression in clinical medulloblastoma specimens." (PMID 28186969, 2017).
renal cell carcinoma (15 papers, 2016 to 2025). "A hypoxia-responsive LTR12B RTE has been reported to act as a cryptic promoter of an alternative isoform of POU5 F1, encoding the pluripotency transcription factor OCT4, producing a likely non-functional version of this tumour-promoting protein in renal cell carcinoma." (PMID 40336011, 2025). "In renal cell carcinoma (RCC), POU5F1 expression is activated by a HIF1-pathway-responsive promoter in the long terminal repeat (LTR) element that is located upstream of POU5F1." (PMID 36564568, 2022).
thyroid cancer (13 papers, 2014 to 2025). "A previous thyroid cancer study indicated the mechanism by which DAPK1 regulates OCT4 (POU5F1), which is a master gene that determines CSC properties." (PMID 39057063, 2024). "In thyroid cancer, which is discussed in further detail later, DAPK1 is believed to have a close relationship with OCT4 (POU5F1), the master gene that controls CSC stemness." (PMID 39057063, 2024). "POU5F1 and PAX8 are homeobox-containing transcription factors, a family of genes that play a role in cell fate and differentiation programs, and whose role in cancer is well recognized, particularly PAX8 in thyroid cancer." (PMID 26684754, 2015). "Indeed, in differentiated and undifferentiated thyroid cancers, POU5F1/OCT4 was variably expressed in some cases, but not in others." (PMID 28039458, 2017).
Ewing sarcoma (11 papers, 2010 to 2025). A small round cell tumor that lacks morphologic, immunohistochemical, and electron microscopic evidence of neuroectodermal differentiation. "POU5F1/OCT4 was the most promising new therapeutic target in Ewing sarcoma, interacting with 10 of the 21 prioritised molecular targets and meriting further study." (PMID 36765727, 2023).
head and neck cancer (10 papers, 2017 to 2024). A primary or metastatic malignant neoplasm affecting the head and neck. "Additionally, radiotherapy induced the dedifferentiation of head and neck cancer cells into stem cells and increased plasticity by Yamanaka reprogramming factors (transcription factors Oct4 (Pou5f1), Sox2, cMyc and Klf4) in HPV-negative cell lines." (PMID 30875950, 2019).
atherosclerosis (9 papers, 2019 to 2025). A disease characterized by the build-up of fatty material and calcium deposition in the arterial wall resulting in partial or complete occlusion of the arterial lumen. "A notable exception is the Tcf19gene, which is upregulated upon Pou5f1 promoterdeletion and might be associated with the atherosclerosis pathology due to itspro-inflammatory activity." (PMID 40771854, 2025).
dysgerminoma (8 papers, 2015 to 2025). A malignant germ cell tumor characterized by the presence of a monotonous primitive germ cell population. "OCT4 (POU5F1) shows strong, diffuse nuclear staining in nearly all dysgerminomas, including metastatic and gonadoblastoma-associated cases." (PMID 41373846, 2025).
germinoma (8 papers, 2010 to 2025). A malignant germ cell tumor arising in the central nervous system. "The immunohistochemical markers in current use include CD117/KIT, POU5F1 (OCT3/4), PLAP, and CT45 (germinoma); AFP, SALL4 and glypican 3 [yolk sac tumour (YST)]; CD30 (embryonal carcinoma); and HCG (choriocarcinoma)." (PMID 23861728, 2013). "In addition, most germinomas highly express placental alkaline phosphatase (PLAP), c-kit (CD117), and POU5F1 (OCT3/4)." (PMID 37215600, 2023).